PCNA (proliferating cell nuclear antigen)
Diseases named in the same sentence as PCNA in open-access papers (continued):
Sharing a sentence is not in itself a finding about the gene and the disease.
breast cancer (continued). "All three breast cancer cell lines displayed approximately 10-fold higher GCSH protein expression as well as significantly boosted PCNA contents and moderate lowered ß-actin levels." (PMID 30337557, 2018). "Analysis of breast cancer tissue showed increased PCNA expression over normal tissue nearby and this type of cancer was also correlated with shorter survival." (PMID 30406112, 2018). "PCNA expression was induced by estrogen in breast cancer MCF-7 and by genistein in a time- (at 48 h and afterward) and concentration-dependent manner (at 10(-8) M and above) in Ishikawa cells." (PMID 29849935, 2018). "Although high PCNA expression alone predicts poor survival (P=0.0144, Log-rank test) in breast cancer patients, combining PCNA and metastatic signature together very improves the poor survival prediction (P=1.018e−4, Log-rank test) in the same cancer patients." (PMID 28382931, 2017). "This signature predicted poor survival in breast cancer patients and also correlated with enriched PCNA expression." (PMID 28382931, 2017). "In a recent study, HCG was reported to reduce the proliferation of MCF-7 breast cancer cells by decreasing the expression of proliferating cell nuclear antigen (PCNA) and proliferation-related Ki-67 antigen (Ki-67)." (PMID 28754015, 2017). "Downregulation of p21 by miR-17-5p in turn promotes PCNA (proliferating cell nuclear antigen) activity, where p21 is a negative regulator of PCNA and thus ERα promotes breast cancer cell cycle progression and proliferation in p21/PCNA/E2F1-dependent pathway." (PMID 29050357, 2017). "EPIG-Seq analysis of TCGA human breast cancer RNA-Seq data extracts genes regulated across the various subtypes including PCNA, one of the key marker genes." (PMID 27004791, 2016). "We performed flow cytometry to analyse cell cycle and apoptosis in ER-/Her2+ breast cancer cells, and then we analysed some markers of cell cycle and apoptosis by Western blotting, including PCNA, cyclin E, cleaved caspase-3, procaspase-3 and Bcl-2." (PMID 27494865, 2016). "An elevated expression of PCNA in mammary tumors of DMBA control animals indicates accelerated proliferation of tumor cells." (PMID 26699876, 2016). "Orally administered PE resulted in reduced expression of PCNA in conjunction with lower PCNA LI in tumor sections which strongly suggests antiproliferative mechanisms involved in the observed reduction of the incidence and growth of mammary tumors." (PMID 26699876, 2016). "In this study, we have used rat mammary tumor samples to analyze the expression of PCNA by immunohistochemical technique." (PMID 26699876, 2016). "IHC staining for PCNA in metastatic breast cancer sections of all mice was used to investigate the overall pattern of expression." (PMID 26716512, 2016). "Many of these genes have known roles in cancer gene networks such as the proto-oncogenes JUN and FOS, RAP1A (RAS-related protein 1A), ITGB5, as well as BRCA2 (Breast cancer 2, early onset) and PCNA (Proliferating cell nuclear antigen)." (PMID 26448646, 2015). "As expected, in the largest group of breast cancer patients with ER+ luminal A breast cancer the PCNA metagene and mammaprint signatures significantly predicted poor survival." (PMID 26020648, 2015). "Expression of H3R in breast carcinomas is correlated with the levels of proliferating cell nuclear antigen (PCNA) level and an increased level of malignancy." (PMID 25940798, 2015). "To address the relationship between the TSTSS and proliferation in the clinical breast cancer datasets, we used a meta-PCNA index as a surrogate for proliferation." (PMID 24890385, 2014). "In a subsequent study, we reported that breast cancers in African American and Hispanic women had elevated numbers of these PCNA+ TAMs." (PMID 24205370, 2013). "We then compared the percentage of PCNA-positive cells after 3 and 7 days culture in these two reconstituted breast cancer tissues." (PMID 23206234, 2013).
breast cancer (continued). "Increased PCNA expression was also shown to be related to a shorter disease-free period and overall survival time in patients with breast cancer." (PMID 24403257, 2013). "Tyrosine 211 (Y211) phosphorylation of proliferation cell nuclear antigen (PCNA) coincides with pronounced cancer cell proliferation and correlates with poor survival of breast cancer patients." (PMID 23593472, 2013). "We detected significant reductions in mammary tumor volume, in proportion of living tumor tissue, and in frequency of proliferating cells as indicated by PCNA staining in all TAM-treated groups (G1, G2 and G3)." (PMID 23634930, 2013). "Validating these results in a larger data set would require an independent cohort of breast cancer patients treated with neoadjuvant anthracycline based chemotherapy with IHC staining results for PCNA+ TAMs." (PMID 24205370, 2013). "PCNA is a known cell proliferation marker during the S and G2 phases of the cell cycle in breast cancer cells." (PMID 23593472, 2013). "In the present study, the reduced PCNA LI% observed in TAM-treated rats can be explained by the ability of TAM to inhibit estrogen receptor (ER)-dependent cell proliferation in mammary tumors." (PMID 23634930, 2013). "MCF-7 breast cancer cells were also imaged to determine if PCNA and HLA I colocalization was a common phenomenon, or unique to DB cells." (PMID 23527218, 2013). "We observed similar results using a gene signature-proxy for PCNA+ TAMs in a larger independent set of 425 neoadjuvant-treated breast cancer cases." (PMID 24205370, 2013). "The PCNA LI% within the live tumor areas was significantly higher in mammary tumors from the untreated control group (≥6%) than in those from the TAM-treated groups (≤1%) (p <0.005)." (PMID 23634930, 2013). "Univariate and multivariate analysis of PCNA+ TAMs, Tc/ClassII signature score, and breast cancer outcomes." (PMID 24205370, 2013). "We checked the gene expression correlation between module 2 and meta-PCNA, and found that similar to other many published gene signatures, module 2 expression is strongly correlated to meta-PCNA across five breast cancer data sets." (PMID 23228031, 2012). "Proliferating cell nuclear antigen (PCNA) was decreased in mammary hyperplasia and in mammary tumors when administered γ-TmT." (PMID 22254089, 2011). "In line with this, we have preliminary data demonstrating an association between FBXW7/hCDC4-β methylation and high expression of the proliferation marker PCNA in breast cancer (correlation coefficient r = 0.313, P = 0.022 (n = 52, cohort 1))." (PMID 21122106, 2010). "Our goals were to understand the predictive value of computational ERE detection for an E2-responsive gene and to better define the mechanisms by which estrogen stimulates PCNA gene expression in breast cancer cells." (PMID 18949048, 2008). "We recently demonstrated that estradiol (E2) enhances PCNA mRNA expression in MCF7 breast cancer cells." (PMID 18949048, 2008). "We confirmed that PCNA gene expression is enhanced by E2 exposure in MCF7 breast cancer cells which express ERα and proliferate in response to E2." (PMID 18949048, 2008). "Most studies have observed that high PCNA gene expression correlates with increased metastatic potential and decreased survival in patients with breast carcinoma." (PMID 18949048, 2008). "Similarly, in a DMBA-induced breast cancer model in rats, an elevated number of PCNA-positive cells was reported, indicating enhanced cell proliferation." (PMID 40430573, 2025). "PCNA inhibition has also been explored as a therapeutic target in breast cancer." (PMID 40430573, 2025). "ERα upregulates PCNA and enhances breast cancer cell proliferation." (PMID 40940954, 2025).
breast cancer (continued). "According to subtype analyses, skimmianine’s PCNA- and TNF-α-associated anticancer effects may be more relevant in basal molecular subtypes and C2 immune subtypes of breast cancer." (PMID 40430573, 2025). "In this study, we further examined the clinical significance of a four-gene signature (comprising CDK1, PCNA, EZH2, and BUB1) that may be associated with relapse events in untreated luminal breast cancer patients." (PMID 38831458, 2024). "Moreover, PCNA is also responsible for tumor growth, serving as a marker for breast cancer cell proliferation and prognosis." (PMID 38687509, 2024). "Within breast cancer, similar interactions between PCNA and NKp44 have been observed." (PMID 39205238, 2024). "These include the proliferating cell nuclear antigen (PCNA) and topoisomerase II, which may play significant roles in the pathology of Luminal B breast cancer." (PMID 38256428, 2024). "The inclusion of three additional targets (CCNA2, PCNA, and KIF23) within the APIS BC Subtyping Kit, known to be associated with breast cancer proliferation and expressed across all cell cycle stages, allows for the generation of a more complete proliferation measure." (PMID 38337757, 2024). "PCNA overexpression has been documented in different types of cancer, including breast cancer." (PMID 37373429, 2023). "The proposed algorithm was used to select optimal quantile biomarkers of breast cancer progression based on cancer cells’ cell signal intensity levels of nuclear protein Ki-67, Proliferating cell nuclear antigen, Programmed cell death 1 ligand 2, and Progesterone receptor." (PMID 37481512, 2023). "Downregulation of FBXO43 has been shown to significantly suppress the malignant phenotypes of breast cancer cells, which may be dependent on proliferating cell nuclear antigen (PCNA) degradation and inactivation." (PMID 36765911, 2023). "Interestingly, SeNPs reduced the PCNA expression level in MCF-7 cells, showing their role in suppressing oncogenesis and proliferation in breast cancer by inhibiting PCNA gene expression." (PMID 38138613, 2023). "Identical results also occur in prostate carcinoma and breast cancer that PCNA connects with pathological stage and cellular grade, suggesting PCNA might be a crucial prognostic indicator of malignant tumors." (PMID 36776764, 2023). "Furthermore, NF-κB and proliferating cell nuclear antigen (PCNA) in breast cancer were also downregulated." (PMID 35153781, 2022). "We have already shown that R11-NLS-pep8 can reduce cell viability and promote cell death in various murine and human cancer cell lines and inhibit tumor growth by interfering with the function of intracellular PCNA in the 4T1 breast cancer and the B16 melanoma in vivo models." (PMID 36430528, 2022). "Some assays concluded that knockdown of PCNA repressed breast cancer cells migration and invasion." (PMID 35164019, 2022). "In addition, western blotting indicated that miR-885-3p suppressed the progression of breast cancer cells by downregulating the expression level of PCNA and the expression levels of CDK2/CCNE1 and CDK4/6/CCND1 (Student’s t test, p < 0.05)." (PMID 35383130, 2022). "The expression of key markers associated with proliferation (MKI67, PCNA, CCNB1, MYBL2, BUB1, CCND1), apoptosis (BCL2, CASP7, CASP8, CASP9, CASP3, BAX, APAF1), differentiation (CDH1, CD24, EPCAM, ESR1, NGFR, RUNX1), and breast cancer stemness (CD44, ITGA6, DNER, ALDH1A3, ABCG2, PROCR) was assessed." (PMID 35183258, 2022). "Although the detection of the autoantibodies accepted a raise of interest as a tool for diagnosis, early prediction, and monitoring of treatment response of different therapeutic modalities in cancers including breast cancer, PCNA autoantibodies have been seldom reported." (PMID 34001936, 2021). "PCNA is usually known as a proliferating marker in breast cancer." (PMID 33662042, 2021).
breast cancer (continued). "PCNA has been shown to stimulate diverse protein-DNA and protein–protein communications, while Ki67 has been emphasized in previous work as a cell proliferation marker and an attractive prognostic factor for breast cancer therapy." (PMID 33653378, 2021). "These PCNA+ proliferating TAMs in breast cancer also had high expression of MKI67." (PMID 33144684, 2021). "Besides, in human breast cancer cell line MDA-MB231, G1 arrest induced by α-mangostin was associated with the augmentation of p21waf1/cip1, a decreased expression of proliferating cell nuclear antigen (PCNA) and cyclin D1." (PMID 34885809, 2021). "Reflecting the known proliferative effect of E2 in breast cancer cells and confirming the activation of proliferative pathways in this cell line model, the PCNA index of E2-treated cells was highest (where DOX treatment alone, which is used to induce MR, is equivalent to vehicle treatment)." (PMID 33148314, 2020). "Estrogen receptor alpha could mediated proliferation of human breast cancer via a p21/PCNA/E2F1-dependent pathway." (PMID 31409371, 2019). "Removal of the proliferation component of gene expression by proliferating cell nuclear antigen (PCNA) adjustment via statistical methods has been addressed in numerous survival prediction studies for breast cancer and all cancers in the Cancer Genome Atlas (TCGA)." (PMID 30965671, 2019). "To validate the sequential progression of breast cancer, we investigated the status of molecular markers of proliferation and invasion, such as a proliferating cell nuclear antigen (PCNA) and α-SMA in different paraffin-embedded tissue sections using immunohistochemical analysis." (PMID 29813119, 2018). "In veterinary medicine, the PCNA level is frequently evaluated in cases of mammary cancer." (PMID 30373614, 2018). "Next, we investigated whether the infiltrated PCNA overexpressing cells formed any metastatic growths in the lungs; the lungs are the most attractive soil for the secondary growth of breast cancer cells in a xenograft model." (PMID 29813119, 2018). "Additionally, modulation of PCNA and Cdc2 stability and activity through their association with nuclear EGFR contributes to uncontrolled proliferation and DNA repair in breast cancer cells." (PMID 25997448, 2015). "Furthermore, the inhibitory effect of Smurf2 on breast cancer cell proliferation was confirmed by using proliferation markers such as PCNA and Ki67 which are important regulators of proliferative indices." (PMID 25191523, 2014). "As we have previously reported, PCNA+ TAMs were significantly associated with high grade, hormone receptor (HR) negative breast cancers." (PMID 24205370, 2013). "Relationship between clinical factors and PCNA+ TAMs in breast cancer." (PMID 24205370, 2013). "As proliferation rate is an important factor determining the tumour aggressiveness, the evaluation of PCNA index (the percentage of PCNA- immunopositive nuclei in the investigated tissue sample) is suggested as useful in evaluating the malignancy of breast cancer." (PMID 23206234, 2013). "In breast cancer patients, a higher expression level of PCNA correlated with poor survival rate." (PMID 23593472, 2013). "In addition, increased PCNA Y211 phosphorylation coincides with pronounced cell proliferation, and Y211 phosphorylation in tumors correlated better with poor survival of breast cancer patients than the total PCNA level." (PMID 23593472, 2013). "In addition, increased PCNA Y211 phosphorylation coincides with pronounced cell proliferation, and PCNA Y211 phosphorylation correlates better with poor survival of breast cancer patients in tumors than the total PCNA level." (PMID 23593472, 2013).
breast cancer (continued). "Since high PCNA+ TAM counts are associated with hormone receptor negative (HR-neg) breast cancers and since these HR-neg cancers tend to have worse outcomes, we also examined the Tc/Class II signature and PCNA+ TAMs in HR-neg cases only." (PMID 24205370, 2013). "Furthermore, the cellular expression of PCNA was also significantly reduced in anti-Nodal treated cells from both breast cancer cell lines." (PMID 22577960, 2012). "The statistical explanation for this phenomenon lies in the correlation of a large fraction of the breast transcriptome with one variable, we call it meta-PCNA, which integrates most of the prognostic information available in current breast cancer gene expression data." (PMID 22028643, 2011). "Moreover, low expression levels of PCNA in Tam-treated mammary tissues further confirm the histopathological observations of inhibition of E2-induced proliferation of breast cancer by Tam." (PMID 21966433, 2011). "Therefore, we determined the expression level of PCNA by Western blot analysis, which revealed that aerosol-delivered shOPN decreased PCNA expression in the lung of breast cancer model mice." (PMID 21203518, 2010). "In our experiments, we used known positive sections of corresponding tissue samples as positive controls (such as stomach tissue as the positive control for FHIT; gastric cancer as the positive control for PCNA and breast cancer as the positive control for Ki-67)." (PMID 18366613, 2008). "Moreover, Groehler and Lannigan demonstrated ERK8, which is active in primary mammary cells but inactivated in breast cancer cell lines, interacts with Proliferating Cell Nuclear Antigen (PCNA), thereby preventing its degradation und supporting correct transfer of genetic information." (PMID 39348153, 2025). "PCNA downregulation by skimmianine may disrupt DNA replication and cell cycle progression, reducing its proliferative potential and limiting tumor growth, consistent with studies showing that targeting PCNA can inhibit DNA replication in breast cancer cells." (PMID 40430573, 2025). "Similarly, the PCNA inhibitor ATX-101 has demonstrated anticancer activity in breast cancer models." (PMID 40430573, 2025). "Next, the results of CCK‐8 and Western blot assay showed that the viability of breast cancer cells transfected with either si‐hsa_circRNA_002178‐1 or si‐hsa_circRNA_002178‐2 was inhibited, accompanied with reductions in expression of proliferation‐related proteins PCNA and Ki67 (P < .05)." (PMID 31957232, 2020). "Therefore, whether expression of NCR2 on NK cells from breast cancer patients would impact NK cell activation negatively or positively depends on the expression of inhibiting (PCNA) versus activating (NKp44L) cellular ligands on breast cancer cells." (PMID 28145491, 2017). "Comparing the prognostic value of FGD3 in breast cancer with the prognostic value of genes associated with proliferation such as MKI67, PCNA, and AURKA indicates that FGD3 may offer superior disease progression metrics in all clinically relevant breast cancer subtypes." (PMID 32913979, 2017). "Moreover, >50% of the breast cancer transcriptome was correlated with meta-PCNA." (PMID 22028643, 2011). "Thus, breast cancer appears as the second, after glioma, in which we observed that the DNA hypomethylation characterizing the tumor cells is correlated with the decrease of Dnmt1/PCNA interactions." (PMID 21470401, 2011). "For instance, in breast cancer, SNHG5 regulates proliferation through the SNHG5–miR-154-5p–PCNA axis; in HCC, it sponges miR-26a-5p to relieve repression of GSK3β, leading to Wnt/β-catenin pathway activation and EMT induction." (PMID 41550840, 2026). "PCNA, Ki-67, and TROP2 are commonly used indicators for measuring the malignancy of breast cancer in clinical practice." (PMID 40839237, 2025).